SSTR3 (somatostatin receptor 3)
Diseases named in the same sentence as SSTR3 in open-access papers (continued):
Sharing a sentence is not in itself a finding about the gene and the disease.
autism spectrum disorder (1 paper, 2023). A spectrum of developmental disorders that includes autism, and Asperger syndrome. "SSTR3 agonists significantly modulate excitatory synaptic properties, perturbating neuron excitatory–inhibitory balance (E/I), a parameter frequently altered in many brain disorders, including autism spectrum disorder (ASD)." (PMID 37444563, 2023).
Bardet-Biedl syndrome (1 paper, 2011). A ciliopathy with multisystem involvement. "Somatostatin Receptor-3 is a membrane-bound GPCR localized to the primary cilium only if proteins implicated in the human ciliary disorder Bardet–Biedl syndrome (BBS) are present." (PMID 22046444, 2011).
brain infarct (1 paper, 2021). "Accordingly, SST and a related peptide, cortistatin-14, and the synthetic SSTR2, SSTR3, and SSTR5 agonist octreotide significantly reduce brain infarct size in a middle cerebral artery occlusion model." (PMID 34803662, 2021).
breast carcinoma (1 paper, 2023). "Furthermore, SSTR2 and SSTR3 regulate intracellular signaling and apoptosis in receptor and cell-specific manner in breast cancer cells." (PMID 38203605, 2023).
breast tumor (1 paper, 2006). "Significantly, SSTR3, which is well expressed in breast tumor tissues, was relatively poorly expressed in these cell lines." (PMID 16519802, 2006).
diabetes (1 paper, 2025). "In the present study, we provide evidence that PDAC-associated diabetes is distinguished by a global downregulation of key islet hormones (INS, GCG) as well as β-cell-enriched transcription factors such as MAFA and PAX4, and hormone receptors such as GCGR, SSTR3 and SSTR5." (PMID 40244011, 2025). "Of the major islet hormones only expression of SST was not significantly reduced in diabetes-associated PDAC, although both Somatostatin Receptor 3 (SSTR3) and SSTR5 which allow paracrine signaling of somatostatin to surrounding α- and β-cells were decreased." (PMID 40244011, 2025).
hepatocellular carcinoma (1 paper, 2023). A malignant tumor that arises from hepatocytes. "SSTR3-induced cytotoxicity has been reported in hepatocellular carcinoma cells upon treatment with OCT." (PMID 38203605, 2023).
Hypoglycemia (1 paper, 2021). A decreased concentration of glucose in the blood. "If SSTR-2, SSTR-3 and SSTR-5 are not expressed or have a low tumor expression, SSAs can lead to paradoxical hypoglycemia because they also inhibit counterregulatory hormone secretion (i.e., glucagon and growth hormone)." (PMID 34199977, 2021).
lymph node metastases (1 paper, 2021). "SSTR3 expression indicated an increased risk for shorter survival and correlated with lymph node metastases among pulmonary carcinoid-tumor patients." (PMID 35008325, 2021).
lymphoma (1 paper, 2021). A malignant (clonal) proliferation of B- lymphocytes or T- lymphocytes which involves the lymph nodes, bone marrow and/or extranodal sites. "Fibrous bands characteristic of nodular sclerosis subtype of HL showed SSTR3 immunopositivity in 44% of cases but staining in connective tissues was seen in other lymphomas and tissues as well." (PMID 34307181, 2021).
malignant laryngeal tumors (1 paper, 2016). "For other SSTR members, there was very little expression of SSTR3 detected in benign and pre-malignant specimens and malignant laryngeal tumors." (PMID 26796520, 2016).
myocarditis (1 paper, 2024). Myocarditis is a condition that is characterized by inflammation of the heart muscle (myocardium). "Secondly, it would have been of additional interest to study even the expression of SSTR3 on inflammatory cells in different forms of myocarditis." (PMID 39518342, 2024).
Obesity (1 paper, 2015). Accumulation of substantial excess body fat. "Other genes, such as Nlk, which was recently found as part of potential susceptibility loci for obesity, and Sstr3 were also changed in cKO mice." (PMID 25629159, 2015).
seminoma (1 paper, 2013). A radiosensitive malignant germ cell tumor found in the testis (especially undescended), and extragonadal sites (anterior mediastinum and pineal gland). "Somatostatin receptor 3 (Sstr3) is an established ciliary localized receptor that is known to be lost in seminomas." (PMID 23599692, 2013).
small cell lung carcinoma (1 paper, 2017). Small cell lung cancer (SCLC) is a highly aggressive malignant neoplasm, accounting for 10-15% of lung cancer cases, characterized byrapid growth, and early metastasis. "The small cell lung cancer cell line NCI-H69 was devoid of SSTR1 expression but strongly expressed SSTR2, SSTR3, and SSTR5." (PMID 29282035, 2017).
thyroid tumor (1 paper, 2022). A benign or malignant neoplasm affecting the thyroid gland. "These “fourth-generation analogs” have been reported to show very high affinity for SSTR2, SSTR3, and SSTR5 and intermediate-high affinity for SSTR4, which possibly make them good candidates for thyroid tumor cells that express high levels of SSTR3 or 5, despite low expression of SSTR2." (PMID 35453992, 2022).
type 2 diabetes (1 paper, 2023). "We validated our genetic knockdown results using pharmacologic agents, via selective SSTR3 antagonism which as a therapeutic approach has shown promise as a treatment for type 2 diabetes by boosting insulin secretion in preclinical models and in human islets ex vivo." (PMID 37660302, 2023).
tumor (32 papers, 2012 to 2025). "In comparison, the SSTR3 and -4 expression level is normally detected low in both control and tumor tissues and both receptors expression is linked to the stage of tumor." (PMID 38203605, 2023). "The activation of Sstr3 by somatostatin/SSAs or its overexpression has been associated with the induction of apoptosis in various normal and tumor cells." (PMID 34205778, 2021). "The SSTR3 expression level in tumor tissues was evaluated by both RT-qPCR and Western blot analyses." (PMID 38612419, 2024). "Amongst all SSTR subtypes, SSTR3 is the key receptor subtype that inhibits tumour cell proliferation via the induction of apoptosis." (PMID 38203605, 2023). "SSTR2/SSTR3 mediated cell proliferation and apoptosis has also been proved to understand the molecular interactions involving SSTRs in tumor biology." (PMID 35053382, 2022). "Of note, in gonadotroph tumours, it would have been interesting to also compare S100B + cells to SSTR3 + cells." (PMID 35139928, 2022). "Metastasis samples in our cohort had increased SSTR3 cytoplasmic expression compared with primary tumor samples." (PMID 35008325, 2021). "It has been shown that apoptosis is mainly mediated by activation or ectopic expression of SSTR3 (among the various receptors) in several normal and tumor cell types." (PMID 34205778, 2021). "Besides, co-expression of SSTR2 and SSTR3 modulates anti-proliferative signaling and apoptosis, which is also benefit to tumor biology research." (PMID 35053382, 2022). "Given that female rats express a higher basal level of Sstr3 and some of their tumors showed shrinkage during treatment with pasireotide, we checked whether this tumor reduction was due to the induction of apoptosis." (PMID 34205778, 2021). "Our study provides new insights in SSTR2/SSTR3 mediated signaling which might help in better understanding of the molecular interactions involving SSTRs in tumor biology." (PMID 22651821, 2012). "Additionally, the fact that tumors in female rats at baseline express significantly higher levels of Sstr3 than those in males may account for the potent suppressive effect of pasireotide on tumor growth in female rats." (PMID 34205778, 2021). "Anti-tumoral bystander mechanisms also suppressed tumor angiogenesis in peripheral tumor vessels; in vivo SSTR2 transfer into human PDAC tumors markedly reduced microvessel density and VEGF expression, while Sstr3 was upregulated." (PMID 40134804, 2025). "Quantification of the SSTR3, SSTR2, and SSTR5 transcript levels in tumor tissues revealed a similar expression of SSTR3 compared to SSTR2 and SSTR5 in our cohort of patients." (PMID 38612419, 2024). "For instance, 111In-DOTA-NOC has increased affinity towards SSTR3 and 5, along with a high affinity to SSTR2, thus potentially allowing for further optimization of SSA-based tumor imaging." (PMID 35712243, 2022). "For both, SSTR3 and SSTR4, the few cases with higher expressions had a higher rate of tumor recurrences with 33.2% (p = 0.0351) and 37.5% (p = 0.0390), respectively." (PMID 34601710, 2022). "Sparsely granulated tumours (SGST) differed from the other subtypes in expression of SSTR2A, SSTR3, SSTR5 and E‐cadherin and occurred more often in young." (PMID 33491286, 2021). "The monoclonal antibodies against SSTR1, SSTR2, SSTR3, SSTR5, and CXCR4 produced distinct immunostaining of the plasma membrane, but also of the cytoplasm of the HCC and CCC tumor cells." (PMID 29282035, 2017). "SSTR3, SSTR2, and SSTR5 expression in tumor tissues was analyzed by qRT-PCR and Western blot." (PMID 38612419, 2024).
tumor (continued). "In fact, ITF2984 showed a significant radiologic tumor response and a compensatory upregulation of SSTR3 mRNA only in female rats, while no significant antitumor effect was observed in male rats with lower SSTR3 levels." (PMID 37444563, 2023). "Furthermore, in comparison to low-grade tumours, relatively high expression of SSTR2 and SSTR3 has been reported in low intermediated groups of SCLC." (PMID 38203605, 2023). "SSTR1 was expressed in three (75%), SSTR3 in two (50%), SSTR4 in 0% and SSTR5 in 0% of the GLP-1R-negative tumours, compared to eleven (23%) (p = 0.055), fifteen (31%) (p = 0.589), 0% and three (6%) (p = 1.000) in GLP-1R-positive tumours, respectively." (PMID 37894845, 2023). "Univariate analysis demonstrated a higher rate of tumor recurrence for increased expression scores for SSTR2A, SSTR3, and SSTR4 (p = 0.0312, p = 0.0351, and p = 0.0390, respectively), while high expression levels of SSTR1 showed less frequent tumor recurrences (p = 0.0012)." (PMID 34601710, 2022). "Using ROC analysis in tumours defined by cytokeratin 18 expression (n = 101), low expression of E‐cadherin was the most sensitive and specific feature of SGST (AUC = 0.97, P < .0001) followed by SSTR2A (AUC = 0.82, P < .0001) and SSTR3 (AUC = 0.72, P = .0001)." (PMID 33491286, 2021). "On the contrary, Vt in the tumor was lower for 68Ga-DOTANOC than for the other two tracers, and although 68Ga-DOTANOC has higher affinity for SSTR2 than 68Ga-DOTATOC, it also has affinity for SSTR3 and SSTR5." (PMID 25369268, 2014). "Hence, VEGF, tumor vascularization, and Sstr3 expression were identified as novel targets for the SSTR2-mediated anti-tumor bystander effect." (PMID 40134804, 2025). "Indeed, ITF2984 suppressed tumor growth in female rats having high baseline expression of the Sstr3 gene, but not in male rats with lower Sstr3 gene expression." (PMID 37444563, 2023). "Interestingly, there was a negative linear correlation between relative tumor volume and Sstr3 expression (p = 0.019), suggesting that PTs with higher Sstr3 levels grew less rapidly." (PMID 34205778, 2021). "Within the 18 tumour specimens, SSTR2A showed the highest immunoreactivity with a median IRS of 8, while SSTR1, SSTR2B und SSTR5 had a median IRS of 3 and SSTR3 und SSTR4 showed no immunoreactivity (median IRS = 0)." (PMID 37707754, 2023). "Differences related to tumor grade were evident for SSTR1 (p = 0.036), SSTR2 (p = 0.009) and SSTR5 (p = 0.029), while differences for SSTR3 (p = 0.059) were non-significant." (PMID 34830858, 2021).
cancer (11 papers, 2013 to 2025). A tumor composed of atypical neoplastic, often pleomorphic cells that invade other tissues. "While there are few studies reported the association between the SSTR3 expression and immune microenvironment in human cancer." (PMID 34114970, 2021). "SSTR3 is also expressed outside the brain, mostly in gastrointestinal tract and testes, and is a promising drug target for diabetes and cancer." (PMID 33372037, 2021). "Furthermore, three genes—Cxorf65, SSTR3, and ART3—had a testis-associated expression pattern and might represent novel Cancer/Testis antigens." (PMID 35145509, 2021). "Mechanistically, LLNLR-299G3.1 bound to cancer-associated RNA binding proteins and regulated the expression of cancer-related genes, including OSM, TNFRSF4, HRH3, and SSTR3." (PMID 37415734, 2023). "The expression of SST, SSTR2, SSTR3 and SSTR5 mRNA in the normal and cancer groups was detected using RT-PCR." (PMID 24260078, 2013). "Furthermore SSTR3, -4 and -5; SSTR3 and -5; and SSTR2, -3 and -5 are also expressed in HT-29, Caco-2 and HCT119 cancer cells, respectively." (PMID 38203605, 2023). "Thus, we could draw a conclusion that the SSTR-3 mRNA expression among carcinous tissue, adjacent tissue of cancer, and non-carcinous tissue were similar." (PMID 25890201, 2015).
infection (1 paper, 2018). The state of being infected such as from the introduction of a foreign agent such as serum, vaccine, antigenic substance or organism. "The data are also inconsistent with a previous study that examined SSTR3 expression in the ileum of S. mansoni-infected mice eight weeks post-infection." (PMID 29522573, 2018). "The levels of jejunal SSTR1, SSTR2 and SSTR3 mRNA transcripts increased by more than 98% from day 14 to day 37 post-infection." (PMID 29522573, 2018). "The present study demonstrated that octreotide therapy, administered at 50 μg/kg/day by intraperitoneal injection from day 10 to 17 post-infection, decreased mRNA levels of SSTR1 and SSTR2 on day 14 post-infection, although it increased mRNA levels of SSTR1, SSTR2 and SSTR3 on day 50 post-infection." (PMID 29522573, 2018). "On day 50 post-infection, previously infected, octreotide-treated animals exhibited significantly elevated levels of SSTR1, SSTR2 and SSTR3 mRNA compared with previously infected, untreated rats (p<0.05 and p<0.01, respectively)." (PMID 29522573, 2018). "The quantitative PCR results demonstrated that on day 14 post-infection, SSTR1, SSTR2 and SSTR3 mRNA comprised approximately 85%, 12.5%, and 2.5% of SSTR subtypes, respectively in the unweaned rat model." (PMID 29522573, 2018). "Octreotide therapy down-regulated the expression of SSTR2 on day 37 post-infection but significantly increased expression of SSTR1, SSTR2 and SSTR3 on day 50 post-infection." (PMID 29522573, 2018). "Although SSTR1 and SSTR2 expression levels were increased following infection, SSTR3 mRNA was not significantly modified on days 14, 37 and 50 post-infection." (PMID 29522573, 2018). "SSTR1 and SSTR3 mRNA transcript levels were not significantly increased in previously infected, untreated animals on day 37 post-infection compared to the infected, treated and non-infected control groups." (PMID 29522573, 2018). "Following the period of intestinal parasite clearance, by day 14 post-infection, the mRNA levels of SSTR1, SSTR2, but not SSTR3 were significantly higher in the tissues extracted from the jejunum of C. parvum-infected animals compared with those of the control animals (p<0.05)." (PMID 29522573, 2018).
SSTR3 also shares sentences with these, for which no sentence is quoted: gastric cancer (4 papers); brain disorder (2); colon carcinoma (2); lung carcinoma (2); paraganglioma (2); pheochromocytoma (2); acute lymphoblastic leukemia (1); endometrial cancer (1); gynecologic cancers (1); head and neck cancer (1); Head and neck tumor (1); hereditary spherocytosis (1); insulinomas (1); medulloblastoma (1); melanoma (1); Merkel cell carcinoma (1); non-Hodgkin lymphoma (1); pituitary (1); pituitary Cushing's disease (1); prostate carcinoma (1); rhabdomyosarcoma (1); stomach cancer (1).